TRPM4 (transient receptor potential cation channel subfamily M member 4)
Diseases named in the same sentence as TRPM4 in open-access papers (continued):
Sharing a sentence is not in itself a finding about the gene and the disease.
breast carcinoma (22 papers, 2015 to 2025). "Recent studies have also highlighted that TRPM4 is implicated in chemoresistance in breast carcinomas." (PMID 41503337, 2025). "TRPM4 itself was recently shown to be upregulated in breast cancer, where it was associated with epithelial-to-mesenchymal transition (EMT) gene sets spurring our interest to further investigate its role in bCSCs." (PMID 34680485, 2021). "We recommend that validation at the protein level in larger series of breast cancer cases is required to resolve this, as well as to validate the association of TRPM4 with AR protein expression." (PMID 32484822, 2020). "Association of TRPM4 mRNA expression with clinico-demographical and pathological parameters of TCGA breast cancer patients (n = 500)." (PMID 32484822, 2020). "In conclusion, our study demonstrated frequent TRPM4 expression in breast cancer associated with poorer clinical parameters, and that its expression was associated with ER signaling and EMT." (PMID 32484822, 2020). "This is suggestive of the causative roles of TRPM4 in breast cancer metastasis and invasion into axillary lymph nodes." (PMID 32484822, 2020). "In conclusion, TRPM4 protein expression is upregulated in breast cancers associated with worse clinico-demographical parameters, and TRPM4 potentially regulates estrogen receptor signaling and EMT progression in breast cancer." (PMID 32484822, 2020). "Associations of TRPM4 transcript levels (median cut-off) with clinico-demographical and pathological parameters were also examined in the TCGA dataset of breast cancer cases (n = 500)." (PMID 32484822, 2020). "Association of TRPM4 protein expression with clinico-demographical and pathological parameters of breast cancer patients (n = 99)." (PMID 32484822, 2020). "Moreover, in a gene set enrichment analysis of three breast cancer gene expression profiling data sets, TRPM4 expression was shown to be associated with EMT gene sets and estrogen response gene sets." (PMID 33562811, 2021). "We aimed to examine the functional relevance of TRPM4 in normal breast epithelium and breast cancer cases (three GEP datasets for each group) by associating the gene sets (Hallmark collection of the MSigDB) enriched according to TRPM4 transcript expression through GSEA." (PMID 32484822, 2020). "Herein, we examined TRPM4 protein expression profile by immunohistochemistry (IHC) in breast cancer cases compared with normal breast ducts, its association with clinico-demographical parameters, and its potential function in breast cancers by Gene Set Enrichment Analysis (GSEA)." (PMID 32484822, 2020). "TRPM4-CaM interactions in breast cancer can promote migration and shrinkage of tumour cells by increasing activity levels and channel sensitivity." (PMID 40078961, 2025). "COX proportional hazards regression identified TRPM4, as an independent prognostic biomarker in breast cancer." (PMID 41235237, 2025). "Through multi-omics analysis of GEO and TCGA cohorts, we identified two sodium homeostasis-related genes, TRPM4 and SLC9A1, as consistently upregulated oncogenes in breast cancer, with significant diagnostic and prognostic relevance." (PMID 41235237, 2025). "It is a prospective regulator of TRPM4 and also considered to be a promising drug target for breast cancer." (PMID 39932272, 2025). "TRPM4 gene was overexpressed in tumorspheres enriched in breast cancer stem cells (bCSCs), and the TRPM4 gene knock-down revealed potential anti-tumor effects by directly reducing stemness properties of bCSCs in vitro." (PMID 36844925, 2022). "TRPM4 is up-regulated in breast cancer cells and influences breast cancer by potentially regulating estrogen receptor signal and EMT pathway." (PMID 35813831, 2022). "Recently, the K+ channel tetramerization domain 5 protein was indicated as a novel TRPM4-interacting protein, which enhances the Ca2+ sensitivity of TRPM4 and thereby promotes the cell migration and contractility observed in breast cancer." (PMID 35056138, 2022).
breast carcinoma (continued). "Two studies reported the involvement of TRPM4 in breast cancer, where its expression was increased on both the mRNA and protein levels." (PMID 35056097, 2021). "Particularly in breast cancer, two recent studies showed that both the mRNA and protein levels of TRPM4 were upregulated in specimens from breast cancer patients." (PMID 34680485, 2021). "TRPM4 inhibition reduced stemness properties of breast cancer stem cells in vitro, therefore TRPM4 can be a novel therapeutic target." (PMID 35056097, 2021). "In two recent studies, TRPM4 was reported to be upregulated in breast cancer samples at both the mRNA and protein levels." (PMID 33562811, 2021). "In contrast to what is reported on prostate and breast cancer, decreased TRPM4 expression in endometrial cancer correlates with increased EMT and an unfavorable prognosis." (PMID 34360952, 2021). "Recently, a similar role of TRPM4 in the regulation of the EMT process was reported in regard to breast cancer." (PMID 34360952, 2021). "TRPM4 transcript was more highly expressed in breast cancer cell lines (n = 60) compared with 38 other cancer types with the exception of Ewing’s sarcoma (n = 12) with higher TRPM4 expression." (PMID 32484822, 2020). "Majority of the breast cancer cases displayed weak TRPM4 intensity (n = 45/99; 45.5%) followed by moderate (n = 30/99; 30.3%) and strong (n = 8/99; 8.1%) intensity." (PMID 32484822, 2020). "Data-mining demonstrated that TRPM4 transcript levels were significantly higher in The Cancer Genome Atlas series of breast cancer cases (n = 1,085) compared with normal breast tissues (n = 112) (p = 1.03 x 10−11)." (PMID 32484822, 2020). "Our IHC findings in tissue microarrays showed that TRPM4 protein was overexpressed in breast cancers (n = 83/99 TRPM4+; 83.8%) compared with normal breast ducts (n = 5/10 TRPM4+; 50%) (p = 0.022)." (PMID 32484822, 2020). "Four cases contained the IHC staining images of both proteins and visualization of the IHC staining images of these four cases suggested that TRPM4 and AR had similar expression profile in breast cancer cells." (PMID 32484822, 2020). "In this study, we showed that TRPM4 protein was overexpressed in breast cancers compared with normal breast epithelial ducts." (PMID 32484822, 2020). "TRPM4 expression was associated with advanced clinical parameters such as higher lymph node status (N1 and N2) and cancer grade (IIb and IIIb) in the TMA breast cancer series." (PMID 32484822, 2020). "In HPA’s breast cancer cases, TRPM4 and AR protein was expressed in 90.9% (n = 10/11) and 100% (n = 12/12) of the cases, respectively." (PMID 32484822, 2020). "The identification of TRPM4 interactions in mechanistic studies may provide valuable insights into the biological role of TRPM4 in breast cancer and facilitate the exploration of molecular targets for the treatment of breast cancer." (PMID 40078961, 2025). "With the potency, in vivo tolerability,pharmacokinetics, and TRPM4-dependence of ErSO-TFPy established,an evaluation was made in a cell culture of how ErSO-TFPy compares with other clinically used or emerging drugs for ERα+breast cancer." (PMID 40028352, 2025). "This study elucidates the pathogenic roles of TRPM4 and SLC9A1 in breast cancer progression." (PMID 41235237, 2025). "Mutations in TRPM4 and SLC9A1 were observed in 32 high-grade breast cancer tissues." (PMID 41235237, 2025). "Although somatic mutations in TRPM4 and SLC9A1 are relatively rare events in breast cancer overall, the specific mutations that do occur may offer valuable functional insights." (PMID 41235237, 2025). "Interestingly, in both TN and ER+ breast cancer cells, the same family member, TRPM4, and its regulatory protein KCTD5 were upregulated and involved in the cell migration process." (PMID 39633507, 2024).
breast carcinoma (continued). "Gene Set Enrichment Analysis (GSEA) has also indicated a notable association between TRPM4 transcripts and the EMT gene set, suggesting that this protein may promote breast cancer cell spread by inducing the EMT process." (PMID 39633507, 2024). "Notably, in two recent studies, TRPM4 expression was reported to be upregulated in breast cancer samples at both the mRNA and protein levels." (PMID 39041239, 2024). "No TRPM4 c.25-1 G > T variant was found in a female member (III-1) diagnosed with breast cancer at the age of 73 years, whose colonoscopy was negative until the age of 74 years, as with her two sons (IV-1 and IV-2)." (PMID 35158942, 2022). "Finally, the TRPM4 blocker 9-phenantrol was also used due to a recently identified role of TRPM4 in breast cancer." (PMID 34884612, 2021). "TRPM4 mRNA was significantly upregulated in breast cancer tissue compared to normal breast tissue." (PMID 33562811, 2021). "In conclusion, our data suggest that TRPM4 is a mediator of stemness in breast cancer in vitro and its inhibition may hold promise as an efficient complementary therapeutic approach along with standard treatments." (PMID 34680485, 2021). "Moreover, a correlation was described between increased histology scores, including poorly differentiated and highly proliferative tissues from intermediate and high-graded breast cancer, and increased TRPM4 expression." (PMID 33562811, 2021). "Additionally, in an independent immunohistochemistry study analyzing 99 breast cancer samples, TRPM4 protein was found to be significantly overexpressed in breast cancer tissue compared to normal breast ducts." (PMID 33562811, 2021). "Our results also suggest that TRPM4 can be used as a druggable target in breast cancer." (PMID 34680485, 2021). "To gain some insight into the mechanisms that TRPM4 employs to regulate breast cancer stemness, we selected several molecules that participate in these pathways and showed considerable expression in our system and interrogated their mRNA levels in TRPM4 k/d MCF-7 tumorspheres by RT-qPCR." (PMID 34680485, 2021). "TRPM4 thus represents a potential therapeutic target in breast cancer." (PMID 32484822, 2020). "TRPM4 transcript expression was associated with EMT gene set in breast cancer cases but not in normal breast epithelium cases as demonstrated in this study, indicating its potential involvement in triggering EMT for breast cancer cells metastasis." (PMID 32484822, 2020). "Essentially, in a series of normal breast tissue samples (n = 5) and breast cancer cases (n = 43), the authors demonstrated that TRPM4 mRNA expression was significantly higher in breast cancers or patients with higher breast cancer stage, comparable with the observations in our study." (PMID 32484822, 2020). "TRPM4 contributes functionally to the pathophysiology of several cardiac diseases, migration of immune and vascular endothelial cells, and proliferation of breast cancer cells." (PMID 26496025, 2015). "Moreover, TRPM4 is responsible for stemness mediation in breast cancer." (PMID 35804889, 2022). "We suggest that TRPM4 plays a key role in stemness mediation, and its inhibition may represent a novel therapeutic modality against bCSCs contributing in the improvement of breast cancer treatments." (PMID 34680485, 2021). "Our results suggest that TRPM4 is a novel bCSC-regulator, and its targeting may lead to a significant reduction of this aggressive subpopulation and may enhance therapeutic results in breast cancer." (PMID 34680485, 2021). "The TCGA-BRCA cohort analysis emphasizes a potential interplay of metabolic genes like NDUFS1, TRPM4, ARMCX5, SLCO6A1, and epigenetic axis genes like SETDB1 and USP37 in the oncogenesis and prognosis of breast carcinomas." (PMID 41503337, 2025). "The functional states of TRPM4 and SLC9A1 in breast cancer were investigated using the CancerSEA database." (PMID 41235237, 2025).
breast carcinoma (continued). "Consistent with these advancements, our analysis reveals SETDB1, NDUFS1, ARMCX5, TRPM4, and SLCO6A1 as significantly altered genes in high-grade breast carcinomas." (PMID 41503337, 2025). "TRPM4 and K+ channel tetramerization domain 5 (KCTD5) protein expressions are increased in different breast cancer samples." (PMID 36844925, 2022). "Both TRPM4 and KCTD5 mRNA expression was shown to be increased in triple negative samples, a more aggressive subtype of breast cancer that lacks specialized treatment, as well as in ER+/PR+ samples." (PMID 33562811, 2021). "We observed that TRPM4 was expressed in half a proportion of normal breast ducts but expressed in all DCIS cases with similar frequency and intensity distribution as breast cancer cases." (PMID 32484822, 2020). "In addition, according to TNM classification, The expression of TRPM4 was elevated in stage IIB, IIIA, and IV, also in breast cancers with lymph node spread (N1-N2)." (PMID 40078961, 2025). "TRPM4 and SLC9A1 is a novel prognostic biomarker and potential therapeutic target in breast cancer." (PMID 41235237, 2025). "TRPM4 silencing reduced the CSC fraction and impaired its stemness properties, suggesting that this ion channel is critical for CSC maintenance and activity in breast cancer." (PMID 34680485, 2021). "The breast cancer tissue displayed TRPM4-specific staining in the cytoplasm and membrane of breast cells, whereas the surrounding stromal cells were negative for TRPM4." (PMID 33562811, 2021). "Half of the NBT cases (n = 5/10; 50%) were negative for TRPM4, and TRPM4 protein was significantly overexpressed in breast cancers (n = 83/99 TRPM4+; 83.8%) compared with normal breast ducts (n = 5/10 TRPM4+; 50%) (p = 0.022)." (PMID 32484822, 2020). "Therefore, the primary clinical relevance of TRPM4 and SLC9A1 in breast cancer is more robustly underscored by their frequent mRNA/protein overexpression and strong association with poor prognosis, as demonstrated throughout our study, rather than by their mutational status." (PMID 41235237, 2025). "We thus set out to investigate the expression profile of TRPM4 in breast cancers, and to examine the potential roles of TRPM4 in the disease based on its expression profile in gene expression profiling (GEP) datasets of breast cancer tissues compared with normal breast epithelium tissues." (PMID 32484822, 2020).
colorectal cancer (19 papers, 2018 to 2025). A primary or metastatic malignant neoplasm that affects the colon or rectum. "It has also been suggested that high expression of TRPM4, from the same family, is associated with aggressive tumor features and metastasis in colorectal cancer." (PMID 33401247, 2020). "However, a previous study indicated that TRPM4 is highly expressed in tumor buds of human colorectal tumors and is associated with proliferation, cell cycle regulation, and invasion of colorectal cancer cells." (PMID 40313460, 2025). "Another study revealed that TRPM4 gene defects mechanically engaged intestinal barrier integrity by depressing the generation of ROS and decreasing mucus production, thus promoting chronic bowel inflammation, a risk factor for colorectal cancer." (PMID 37892239, 2023). "A recent study described the role of TRPM4 in the cancer hallmark functions of colorectal cancer." (PMID 33562811, 2021). "TRPM4 is also overexpressed in diffuse large B-cell lymphoma associated with worse survival, cervical cancer and colorectal cancer where it could induce proliferation and invasion of colorectal cancer cells." (PMID 32484822, 2020). "For colorectal cancer, TRPM4 mRNA expression has been described as either decreased or unchanged relative to control tissues." (PMID 41562086, 2025). "A recent study has shown that TRPM4 upregulation and its conductivity control the viability and cell cycle of colorectal cancer cells." (PMID 37892239, 2023). "Whole-genome sequencing and bioinformatics analysis on unique colorectal cancer families revealed two attractive candidate predisposition genes, CYBA and TRPM4, each with a loss-of-function variant." (PMID 35158942, 2022). "In this study, we show that calcium-induced exocytosis in the colorectal cancer cell line HCT116 is dependent on TRPM4." (PMID 35681487, 2022). "We demonstrated that TRPM4 plays a role in Ca2+-induced exocytosis in the colorectal cancer cell line HCT116." (PMID 35681487, 2022). "We have previously shown that TRPM4 is a novel potential biomarker candidate for colorectal cancer (CRC)." (PMID 34771564, 2021). "The importance of TRPM4 ion conductivity in modulation of viability and cell cycle shift makes TRPM4 a potential target in the treatment of colorectal cancer." (PMID 35056097, 2021). "For colorectal cancer, TRPM4 mRNA expression has been reported to be either decreased or unchanged in comparison to the control tissue." (PMID 33562811, 2021). "Stable overexpression of the D984A dominant-negative TRPM4 splice variant in the colorectal cancer cell line HCT116 resulted in the complete inhibition of the current without a reduction in TRPM4 protein expression." (PMID 35056138, 2022). "In colorectal cancer the expression pattern of TRPM4 is contradictory." (PMID 35056097, 2021). "We recently described the role of TRPM4 in colorectal cancer (CRC)." (PMID 34771564, 2021). "Three studies investigated TRPM4 expression levels in colorectal cancer." (PMID 33562811, 2021). "TRPM4 expression has also been reported as being significantly downregulated in colorectal cancer compared to normal tissue, suggesting a correlation between decreased TRPM4 expression, loss of the epithelial cell phenotype and increased malignant characteristics in carcinomas in general." (PMID 34936030, 2021). "Moreover, colorectal cancer cell clones with TRPM4 knockout showed decreased migration and invasion." (PMID 32484822, 2020). "In contrast, low expression of TRPM4 was found in colorectal cancer indicating that it may also serve as a protective factor." (PMID 31105744, 2019). "Up to now, the involvement of TRPM4 in colorectal cancer (CRC) pathophysiology remains unknown." (PMID 31441200, 2019).
colorectal cancer (continued). "In the case of native TRPM4 channels, NBA was the most potent blocker, with an IC50 of 0.13 μM in the HCT116 colorectal cancer cell line, while LBA was slightly less potent compared to CBA (IC50 values of 1.84 and 1.17 μM, respectively)." (PMID 35056138, 2022). "In colorectal cancer (CRC), TRPM4 is upregulated, and its conductivity plays a role in the regulation of viability and cell cycle of CRC cells." (PMID 34771564, 2021). "Previously, we have shown that TRPM4 is the main source of Ca2+-activated Na+ entry in the colorectal cancer (CRC) cell line HCT116 and that TRPM4 ion conductivity is involved in the regulation of cellular functions, such as cell viability and cell cycle in different CRC cells." (PMID 35681487, 2022). "On the contrary, the TRPM4 current of rat dental follicle stem cells, the HCT116 colorectal cancer cell line, and TRPM4-expressing human embryonic kidney (HEK) cells showed no desensitization despite the tight-seal whole-cell recording condition." (PMID 35056138, 2022). "TRPM4 was more intensely expressed in tumor buds of colorectal cancer than normal ducts of non-malignant colorectal tissues." (PMID 32484822, 2020). "It would be interesting to define the role of endothelial TRPV channels in angiogenesis and carcinogenesis as recent published data implies that TRPV3, TRPV4, TRPV5, TRPM4 and TRPC6 may be thought of as potential genes contributing to colorectal cancer tumorigenesis." (PMID 29914124, 2018).